RNU2-11P (RNA, U2 small nuclear 11, pseudogene)
Gene: Small nuclear RNA gene on chromosome 3 (195,928,589 to 195,928,775, reverse strand). Ensembl gene ENSG00000239122.
Homologues: Orthologues: chimpanzee U2 (99% identical), mouse Gm23118 (53% identical), mouse Gm55074 (48% identical), macaque U2 (47% identical), tropical clawed frog U2 (46% identical), tropical clawed frog U2 (44% identical), guinea pig U2 (43% identical), rabbit U2 (41% identical), dog U2 (40% identical), rabbit U2 (37% identical), pig U2 (36% identical), rat LOC120099531 (29% identical). Paralogues in human: RNU2-59P (73% identical), RNU2-26P (72% identical), U2 (72% identical), RNU2-57P (71% identical), U2 (71% identical), RNU2-6P (71% identical), RNU2-2 (70% identical), RNU2-36P (70% identical), RNU2-48P (69% identical), RNU2-4P (69% identical), RNU2-64P (69% identical), RNU2-20P (68% identical), and 66 more.